TNF (tumor necrosis factor)
Diseases named in the same sentence as TNF in open-access papers (continued):
Sharing a sentence is not in itself a finding about the gene and the disease.
Hyperglycemia (continued). "Proinflammatory cytokines IL-1β, IL-6, IL-18, and TNFα which play major roles in the development and progression of DN are triggered by hyperglycemia and oxidative stress." (PMID 33562428, 2021). "Surprisingly, TNFR1 was the most significantly down-regulated protein in extracellular HUVECs, whereas TNFR2 protein levels were unaffected following TNFα treatment and hyperglycemia." (PMID 34045516, 2021). "Hyperglycemia attenuates expression of miR-15a and miR-16, while Over-expression of these two miRNAs significantly reduces pro-inflammatory factors such as TNF-α, IL-1β, and NF-κB in HRECs under HG situation." (PMID 33995938, 2021). "Of interest, TNFR2 concentrations were not affected and TNFR1 was profoundly down-regulated following TNFα treatment in hyperglycemia condition." (PMID 34045516, 2021). "The primary goal of the present study is to evaluate the intestinal region-dependent effects of chronic hyperglycaemia and immediate insulin treatment on TNFα expression in myenteric ganglia of different gut segments." (PMID 34572059, 2021). "Compared to sustained hyperglycemia, glycemic fluctuation led to further increase in IL-1β, TNFα, RANKL, TLR2/4, IRAK1, and TRAF6 mRNA expression in peri-implant gingival tissues." (PMID 34401982, 2021). "Studies demonstrated that kaempferol plays vital nephroprotective roles associating with inhibiting oxidative stress, proinflammatory cytokines (TNF-α and IL-1β), and fibrosis in DN via inhibiting hyperglycemia-induced activation RhoA/Rho-kinase." (PMID 34349833, 2021). "Taken together, sustained hyperglycemia over several days appears sufficient to induce the expression of proinsulin and TNF-α expression in ST-HSCs, transforming those cells into the major villain that causes diabetic neuropathy." (PMID 33990693, 2021). "In the intracellular fraction of TNFα-stimulated HUVECs in the presence of hyperglycemia, the mean RFU value was 934 compared to 790 in the control HUVECs (fold change = 1.2, p = 5.9 × 10−5)." (PMID 34045516, 2021). "In vivo and in vitro studies showed that hyperglycemia was associated with increased hs-CRP, cytokine 26, and tumor necrosis factor α levels." (PMID 34912898, 2021). "The fold change is a ratio of a mean RFU value of a protein in HUVECs cultured in TNFα in hyperglycemia condition to a mean RFU value of a protein in HUVECs cultured in hyperglycemia alone." (PMID 34045516, 2021). "We comparatively analyzed expression profiles of 1305 proteins measured on the SOMAscan platform in HUVECs cell lysate (intracellular) and supernatant (extracellular) in response to hyperglycemia and TNFα treatment versus hyperglycemia alone condition." (PMID 34045516, 2021). "Suppression of PKC-β and Nox2 has previously been correlated with decreased apoptosis of endothelial cells exposed to pathological stimuli including hyperglycaemia and inflammatory cytokines like TNF-α." (PMID 34398388, 2021). "In this in vitro study, we examined intracellular and extracellular levels of these proteins in human umbilical vein endothelial cells (HUVECs) exposed to TNFα in the presence of hyperglycemia." (PMID 34045516, 2021). "How the human RECs (HRECs) respond to hyperglycemia and tumor necrosis factor-α (TNFα) are different from bovine retinal ECs, and ECs from other vascular beds such as the human brain and umbilical vein (HUVECs) have been reported." (PMID 35054426, 2021). "A high blood glucose or a hyperglycemia condition has been considered to trigger oxidative stress and also increase proinflammatory cytokines, such as IL-1β and TNF-α." (PMID 33996978, 2021). "Hyperglycemia stimulates the production of TNF-α, which increases vascular permeability and neuronal damage, and aggravated cognitive impairment." (PMID 34319254, 2021). "Previous studies have shown that postprandial hyperlipidemia and hyperglycemia increase TNFα levels in healthy and T2D individuals, as well as in IGT subjects." (PMID 34507586, 2021).
Hyperglycemia (continued). "This is in agreement with Puthanveetil and co-workers’ report that MALAT1 is involved in hyperglycemia by inducing inflammatory cytokines such as tumor necrosis factor-alpha (TNF-α)." (PMID 33670447, 2021). "OLETF group with hyperglycemia showed an increase in HbA1c, serum TNF‐α, and muscle SERCA activity, but a decrease in circulating insulin." (PMID 34558206, 2021). "Propranolol improved postischemic hyperglycemia by subsiding oxidative stress and TNF-α-impaired insulin action in the gastrocnemius muscles." (PMID 32492962, 2020). "Hyperglycemia leads to increased inflammatory cytokines of renal tubular epithelial cells and these inflammatory cytokines, such as IL-1, IL-6, IL-18, and TNF-α can directly damage renal tubular cells." (PMID 32073611, 2020). "It is also shown that mitochondrial dysfunction is closely related to telomere shortening, which is fully mediated by elevation of TNFα in AGM depending on hyperglycemia." (PMID 32454945, 2020). "Systematically, hyperglycemia causes AGE formation and increases ROS product and plasma proinflammatory cytokines, including TNF-α and interleukin-6 (IL-6)." (PMID 33013692, 2020). "Hyperglycemia increased levels of inflammatory cytokines such as TNF-α and IL-6 in the serum of STZ-induced diabetic rats." (PMID 32952955, 2020). "Mechanisms of TNF-α association with T2D likely at least partly involved direct stimulation by hyperglycemia TNF-α production and activity in adipose tissue." (PMID 33233515, 2020). "TNF-α and IL-6 are important inflammatory cytokines whose secretion can be stimulated by hyperglycaemia, hyperlipidaemia and other metabolic abnormalities." (PMID 33050458, 2020). "Oxidative stress resulting from hyperglycemia was confirmed to promote expression of inflammatory cytokines such as TNF-α and IL-6, and generation of ROS accelerates myocardial fibrosis via regulating inflammatory and apoptotic signaling." (PMID 32952955, 2020). "TNF-α is one of the most important pro-inflammatory cytokines that can be induced by hyperglycemia and increase the transcription factor NF-κB via stimulation of TNF-α receptors on the surface of the neurons and glia cells." (PMID 32934245, 2020). "We demonstrated that TRAIL significantly attenuated TNF‐α‐ and hyperglycemia‐induced ROS production." (PMID 33080110, 2020). "Compared with healthy controls, an induced hyperglycemia in diabetic patients results in a more pronounced secretion of pro-inflammatory cytokines such as tumor necrosis factor-α (TNF-α) and IL-6." (PMID 32430795, 2020). "In vivo, treatment of HF/HFr-fed mice with MS-275 ameliorated hyperglycemia, insulin resistance, stress signals, and TNF-α expression in skeletal muscle." (PMID 33362555, 2020). "Interleukin (IL-6 and IL-1β) and tumor necrosis factor (TNF-α) are the inflammatory markers that are elevated in hyperglycemia-induced neuropathic patients, implying that the inflammatory condition exists." (PMID 33015629, 2020). "Both TNF-alpha and hyperglycemia promote ROS release and cell apoptosis through PKC-dependent NOX activation." (PMID 33658920, 2020). "Human retinal pigment epithelial cells (ARPE-19) were stimulated with hyperglycemia and the inflammatory cytokines IL-1β and TNFα in order to mimic diabetic retinopathy molecular signs in vitro." (PMID 33396676, 2020). "After 17 hours post activation, TNF-α gene expression recovered its basal level except for the condition hyperglycemia/hypoxia (three times the basal level)." (PMID 31415598, 2019). "In fact, TNF-α levels has been shown to increase with longer duration of disease as well as hyperglycemia and to decrease with insulin and sulfonylurea treatment." (PMID 31042755, 2019). "Hyperglycemia upregulated the expression of pro-inflammatory cytokines such as TNF-α, IL-1, IL-6, chemokines and downregulated the expression of two receptors involved in phagocytosis (CD 36 and Class B scavenger type I receptors)." (PMID 31415598, 2019).
Hyperglycemia (continued). "Long-time hyperglycemia and aging increase production of inflammatory factors, such as IL-6, TNF-α, and CRP, which promote the onset of DPN." (PMID 31781662, 2019). "The combination of hyperglycemia and hypoxia is required to induce a sustained production of pro-inflammatory cytokines as the same phenomenon was observed for TNF-α and IL-6." (PMID 31415598, 2019). "Hyperglycemia reportedly aggravates renal I/R injury by exacerbating the inflammatory response, as indicated by significantly increased TNF-α and IL-1β levels in serum or renal tissues." (PMID 31441362, 2019). "Since hyperglycemia is known to increase levels of pro-inflammatory cytokines such as IL-1β and TNF-α in the diabetic retina, these factors presumably exert their effect on neuritogenesis as observed in our study." (PMID 31607843, 2019). "A similar effect was obtained in our study, where higher levels of TNF-α were observed after hyperglycemia exposure." (PMID 31687075, 2019). "The impact of hypoxia and hyperglycemia on the gene expression of TNF- α, IL-1a, IL-6 and GM-CSF was analyzed in detail and compared to the results obtained with the microarray." (PMID 31415598, 2019). "This can translate into low TNF-α expression in POD2B/T2D patients because hyperglycemia can overregulate levels of TNF-α, and other cytokines such as GM-CSF and IL-6, in both healthy and periodontal affected tissues." (PMID 31355282, 2019). "Hyperglycemia plays a key role in the development of this disorder, inducing oxidative stress and release of several cytokines such as IL-1β, TNF-α, TGF-β1, which promote myocardial cell death and fibrosis." (PMID 31835864, 2019). "Both adipocyte hypertrophy and the increased fat pad in both subcutaneous and visceral regions induced the increase in body weight gain and the elevations of TNF-α, NF-κB, hyperglycemia, and poor response of the glucose tolerance test." (PMID 31182993, 2019). "Hyperglycemia increases the expression of pro-inflammatory cytokines such as IL-6, IL-1β, TNF-α, and TGF-β." (PMID 31736745, 2019). "Fenoldopam was more effective than dopamine at controlling hyperglycemia and TNF production in endotoxemic mice." (PMID 30700738, 2019). "As a result, the combination of hypoxia and hyperglycemia has a synergistic effect for long term TNF-α gene expression." (PMID 31415598, 2019). "Of note, FGF21 has been shown to reduce levels of inflammatory mediators including IL-1β, IL-6 and TNFα in the serum of obese/diabetic db/db mice and ameliorates hyperglycemia." (PMID 31312114, 2019). "Both hyperglycemia and inflammatory cytokines such as tumor necrosis factor-α (TNF-α) increase endothelial cell oxidative stress due to increased production and decreased scavenging of reactive oxygen species (ROS)." (PMID 31110559, 2019). "After one hour post LPS activation, the combination of hypoxia and hyperglycemia had a dramatic effect on the expression of TNF-α and IL-6." (PMID 31415598, 2019). "Although these studies focused on vagal regulation of serum TNF levels, our present study now suggests that vagal regulation of hyperglycemia can also contribute to the effects of the vagus nerve in these conditions." (PMID 30700738, 2019). "The role of inflammation was previously demonstrated in the development of T2DM and hyperglycemia was shown to increase the circulating TNF-α and IL-6." (PMID 31442295, 2019). "Long-term hyperglycemia leads to the production of a wide range of pro-inflammatory factors, such as interleukin-6 (IL-6), tumor necrosis factor-α (TNF-α), cyclooxygenase-2 (COX-2)." (PMID 31337431, 2019). "More interestingly, BDNF inhibited hyperglycemia-induced microglial activation and reduced elevated levels of inflammatory factors (TNF-α, IL-6)." (PMID 31165005, 2019). "Vagal stimulation attenuated hyperglycemia and serum TNF levels in sham but only hyperglycemia in splenectomized mice." (PMID 30700738, 2019).
Hyperglycemia (continued). "Previous studies also demonstrated that advanced glycosylation ends triggered by long-term hyperglycemia can stimulate phagocytes to release inflammatory cytokines, including tumor necrosis factor, IL-1β, and IL-6." (PMID 31209719, 2019). "Experimental DM in rodents is associated with β cell apoptosis that leads to hyperglycemia, the macrophage proinflammatory cytokine (IL-1β in combination with IFN-γ and TNF-α), playing an essential role in β cell dysfunction and death." (PMID 30818888, 2019). "BDNF also restores the morphology of activated microglia induced by hyperglycemia close to the resting state and suppresses the increased levels of TNF-α and IL-6." (PMID 31165005, 2019). "It is known that hyperglycemia increases the production of pro-inflammatory cytokines like TNF-α, IL-1β, and IL-6, which act by way of NF-kB." (PMID 29694627, 2018). "On the other side, it has been found that hyperglycemia induces the production of TNF-α through the down-regulation of monocyte cell surface CD33, a transmembrane receptor expressed by monocytes in peripheral blood." (PMID 30577684, 2018). "Physiological hyperglycemia generates increased levels of ROS from mononuclear cells, which activate the release of tumor necrosis factor-α (TNF-α) and increase the inflammatory transcription factor nuclear factor-kappa B (NF-κB)." (PMID 30126412, 2018). "High GI diets induce hyperglycemia, which in turn induces oxidative stress and increases pro-inflammatory cytokines, including IL-6 and TNF-α, among both healthy subjects and those with impaired glucose tolerance." (PMID 29414858, 2018). "BAY 11-7082 protects rats from DN by reducing the expression of inflammatory cytokines including TNF-α, IL-1β, and IL-6, and inhibiting the oxidative damage mediated by hyperglycemia." (PMID 30459606, 2018). "Factors contributing to deregulated neutrophil activity in GDM appear to include hyperglycaemia and the interplay between elevated TNFα levels with a concomitant reduction in its potential regulator A1AT." (PMID 30298053, 2018). "Augmented O-GlcNAc levels in the placenta during hyperglycemia coincided with augmented placental levels of interleukin (IL)-6 and tumor necrosis factor alpha (TNF-α)." (PMID 30298013, 2018). "To determine if extrinsic apoptosis is responsive to hyperglycemia we measured cell death of U937 monocytes in normal and high glucose conditions induced by TNF-α, a stimulus of extrinsic apoptosis." (PMID 29760953, 2018). "In our study administration of STZ results in hyperglycemia and severe oxidative stress, followed by inflammation, that was evidenced by the changes in the cytokines like IL-6, NF-kB, and TNF-α related to inflammation." (PMID 29670899, 2018). "In a similar manner, curcumin exerted antioxidant effect, reducing hyperglycemia and also inhibited macrophages-mediated tumor necrosis factor (TNF) and interleukin-6 (IL-6) release, activated by dying or stressed B cells." (PMID 28194110, 2017). "We, next, examined this interplay between hyperglycemia and TNF-α in a coculture experiment, using BeWo trophoblast-like cells and freshly isolated control neutrophils." (PMID 28659928, 2017). "For example, the activation of NF-κB and release of TNF-α and IL-6 in human monocytes in response to hyperglycemia were suppressed by 3–10 mM luteolin." (PMID 28740538, 2017). "Antioxidant treatment and TNF-α knockdown attenuate high glucose-induced sclerostin expression, suggesting that hyperglycemia induces high sclerostin expression via enhancing the production of reactive oxygen species and TNF-α." (PMID 29240821, 2017). "In concert with hyperglycemia, the inflammatory milieu producing TNF-α is considered a significant contributor to the CVD in T2D mainly through the enhanced oxidative stress." (PMID 29095915, 2017). "In another study of human macrophages, hyperglycemia enhanced the expression of the M1 cytokines TNF-α and IL-1β as well as M2 cytokine IL-1Ra expression." (PMID 29081777, 2017).
Hyperglycemia (continued). "The study demonstrates that hyperglycemia, hyperinsulinemia, hyperleptinemia, and an increase in the tumor necrosis factor (TNF-a) mRNA level occurred in the obese rats are normalized when treated with purple corn diet." (PMID 28970777, 2017). "In obese animals, chokeberry suppressed visceral fat accumulation and hyperglycemia, elevated plasma adiponectin and inhibited the plasma TNF-α and IL6 levels." (PMID 29182628, 2017). "The inhibition of insulin signaling pathway via TNF-α lead to suppression of the regulatory enzymes of fatty acids and glucose capture producing hyperglycemia." (PMID 28505155, 2017). "The mechanisms include hyperglycemia-induced inflammatory processes like nuclear factor kappa-B (NF-κB), tumor necrosis factor-α (TNF-α), interleukin (IL)-1β, and IL-6." (PMID 27463726, 2016). "It is widely accepted that hyperglycemia stress, increases cytokines secretion such as TNF-α, IL-6 and IL-1β and alters gene expression profile in targeted cells." (PMID 27942499, 2016). "Hyperglycemia triggers chronic systemic inflammatory responses and induces the expression of a variety of inflammatory factors, including NFκB, TNF-α and IL-6, which also promote PC progression." (PMID 27413117, 2016). "A recent study indicated that hyperglycemia induced NF-κB activation leading to an increase in inflammatory cytokines, IL-1β and TNF-α level, in diabetic kidneys and an increase in TGF-β1 gene expression in STZ-induced diabetic rats." (PMID 27649140, 2016). "The neutrophils from the CCR2 KO or DEREG chimeric mice with hyperglycemia showed enhanced expression of IL-1β and TNF-α compared with those from the control mice." (PMID 27464894, 2016). "An increased secretion of TNF-α and IL-6 under conditions of hyperglycemia is a finding observed by several authors." (PMID 26861982, 2016). "Lastly, we demonstrated that miR-146a overexpression resulted in the decrease of hyperglycemia-induced elevation of TNFα in REC." (PMID 26997759, 2016). "Our results suggest that miR-146a decreases the levels of hyperglycemia-induced TNFα possibly through the inhibition of HMGB1, TLR4, MyD88, and TRIF/IRF3 signaling." (PMID 26997759, 2016). "We, therefore, demonstrated that the hyperglycemia-induced increase of TNFα levels were decreased in REC when miR-15b/16 are overexpressed." (PMID 25888955, 2015). "Our results show that G. asiatica fruit extract decreases IL-1β and TNF-α induced during hyperglycemia." (PMID 26347423, 2015). "The ability of diabetic stimuli (hyperglycaemia, TNF-α, and palmitate) to modulate angiogenic potential of ND-EC was also explored." (PMID 25950006, 2015). "Various other stimuli also cascade circulating TNF-α, including hyperglycaemia and advanced glycation end product receptors." (PMID 26295054, 2015). "Previous findings by our group have shown that maternal hyperglycemia is also adversely involved in fetal development by changing the placental production of proinflammatory cytokines, that is, TNF-α (tumor necrosis factor alpha)." (PMID 25197655, 2014). "The link between increased TNF-α serum levels and activation of the glycosylating enzyme 2GlcNac-T provides evidence of the complex pathways induced by hyperglycemia." (PMID 25258680, 2014). "The diabetic WT group exhibited elevated TNF-α levels in the retina, approximately 1.5-fold higher than the β-catenin KO mice with the same degree and duration of hyperglycemia." (PMID 25271989, 2014). "OVE26 transgenic type 1 diabetic mice develop hyperglycemia at 2-3 weeks of age and exhibit albuminuria at 3 months of age with mild increases in TNF-α expression and 3-NT accumulation in the aorta." (PMID 23589759, 2013). "Other mediators that can induce OPN upregulation include angiotensin II, transforming growth factor β(TGFβ), tumor necrosis factor α (TNFα), interleukin‐1β (IL‐1β), nitric oxide (NO), hyperglycemia and hypoxia." (PMID 23437160, 2013).